PSCA (prostate stem cell antigen)
Diseases named in the same sentence as PSCA in open-access papers (continued):
Sharing a sentence is not in itself a finding about the gene and the disease.
non-small cell lung carcinoma (6 papers, 2023 to 2025). A group of at least three distinct histological types of lung cancer, including non-small cell squamous cell carcinoma, adenocarcinoma, and large cell carcinoma. "Mucin 1 (MUC1) and prostate stem cell antigen (PSCA) are overexpressed in non-small cell lung cancer (NSCLC)." (PMID 40092990, 2025). "The high expression level of PSCA is observed in several cancers, including non-small cell lung carcinoma (NSCLC), clear cell renal cell carcinoma (CC-RCC), and other cancers." (PMID 38627732, 2024). "In a non-small cell lung cancer (NSCLC) model, a therapeutic combination of CAR T-cells targeting prostate stem cell antigen (PSCA) and mucin 1 (MUC1) effectively eradicated cancer cells expressing PSCA and MUC1." (PMID 38612592, 2024). "In addition, research has shown that the co-application of prostate stem cell antigen (PSCA)-targeted and mucin 1 (MUC1)-targeted CAR-T cells effectively eradicated cancer cells in individuals diagnosed with PSCA + and MUC1 + non-small cell lung cancer (NSCLC)." (PMID 38622705, 2024).
lung carcinoma (5 papers, 2022 to 2024). "Secondly, three genes [ArfGAP With Coiled-Coil, Ankyrin Repeat And PH Domains 2 (ACAP2), Enolase3 (ENO3), and prostate stem cell antigen (PSCA)] showed an upregulation in lung cancer tissue, suggesting their role as an oncogene." (PMID 39199663, 2024). "In lung cancer, the most relevant therapeutic targets include ROR1, EGFR, PD-L1, CD80/CD86, mucin 1 (MUC1), mesothelin (MSLN), carcinoembryonic antigen (CEA), prostate stem cell antigen (PSCA) and human epidermal growth factor receptor 2 (HER2)." (PMID 36873868, 2023).
pancreatic adenocarcinoma (5 papers, 2007 to 2022). "For example, in 2001, SAGE was used to first demonstrate that mesothelin and prostate stem cell antigen (PSCA) were overexpressed in pancreatic adenocarcinoma." (PMID 18954444, 2008). "As a target on cancer cells, we chose the prostate stem cell antigen (PSCA), a glycophosphatidylinositol (GPI)-anchored tumor-associated antigen which is found in a variety of urogenital-related cancers, and various other malignancies such as pancreatic adenocarcinoma and glioblastoma." (PMID 35454835, 2022).
hepatocellular carcinoma (4 papers, 2018 to 2023). A malignant tumor that arises from hepatocytes. "In addition, other TAAs, like erythropoietin-producing hepatocellular carcinoma A2 (EphA2), prostate stem cell antigen (PSCA), and mucin 1 (MUC1), have also been detected in NSCLC and confirmed to be promising targeting antigen for CAR-T cells." (PMID 29769134, 2018).
gallbladder cancer (3 papers, 2013 to 2024). "A study based on 405 gallbladder cancer patients and 247 healthy controls showed that the PSCA haplotype Trs2294008 Ars2978974 conferred low risk of gallbladder cancer in males, while in females, the Trs2294008 Grs2978974 haplotype was related to increased gallbladder cancer risk." (PMID 27050280, 2016). "Our study suggested that overexpression of PSCA and Oct-4 might be closely related to the carcinogenesis, progression, metastasis, or invasive potential and prognosis of gallbladder carcinoma." (PMID 23984394, 2013). "The overexpression of PSCA and Oct-4 was correlated with decreased survival and might serve as important biological marker for reflecting the carcinogenesis, progression, metastasis, or invasive potential and prognosis of gallbladder carcinoma." (PMID 23984394, 2013).
gastric ulcer (3 papers, 2013 to 2024). An ulcerated lesion in the mucosal surface of the stomach. "PSCA antigen is also associated with gastric ulcer, so people who carry the C allele variant rs2294008 are more susceptible to gastric ulcer." (PMID 38627732, 2024). "We here found that variation in the PSCA gene was significantly associated with gastric ulcer." (PMID 23704932, 2013).
peptic ulcer disease (3 papers, 2013 to 2023). A digestive system disease characterized by discontinuation in the inner lining of the gastrointestinal (GI) tract because of gastric acid secretion or pepsin. "In the UK Biobank, ABO, CDX2, CCKBRMUC1, MUC6, FUT2, PSCA, and GAST genes have been identified and found to be associated with peptic ulcer disease." (PMID 36678166, 2023).
acute myeloid leukemia (2 papers, 2012 to 2014). Acute myeloid leukemia (AML) is a group of neoplasms arising from precursor cells committed to the myeloid cell-line differentiation. "The reported tumor stem cell markers also included Aldehyde dehydrogenase (ALDH1), Musashi-1, LgR5, the prostate stem cell antigen (PSCA), Doublecortin and CaM kinase-like-1 (DCAMKL-1), and acute myeloid leukemia (AML) stem cell-surface marker TIM3." (PMID 22634835, 2012).
bladder tumor (2 papers, 2016 to 2022). "The prostate stem cell antigen (PSCA) is also a biomarker highly expressed on the surface of bladder tumor cells." (PMID 36290934, 2022).
cervical cancer (2 papers, 2016 to 2024). A primary or metastatic malignant neoplasm involving the cervix. "We then evaluated the association between the rs2294008 and PSCA protein expression in 50 cervical cancer tissues by IHC assay." (PMID 27001215, 2016). "In addition to rs2294008 variant, two other PSCA variants (rs2976392, rs2978974) were evaluated in the incidence of cervical cancer, but whether these two variants are involved in cervical cancer needs further investigation." (PMID 38627732, 2024). "Taking into account the potential oncogenic role of PSCA in cervical cancer and the attractive statistical significance of the rs2294008 polymorphism among the three GWAS, we aimed to determine the association of the rs2294008 polymorphism with risk of cervical cancer in a Chinese population." (PMID 27001215, 2016).
gastric adenocarcinoma (2 papers, 2015 to 2020). "Genotype frequency of prostate stem cell antigen (PSCA) variation and their association with gastric adenocarcinoma (GAC) risk." (PMID 26006239, 2015).
lymph node metastasis (2 papers, 2013 to 2014). "According to the risk rank, PSCA overexpression was the most significant predicator of short overall survival, followed by lymph node metastasis." (PMID 23984394, 2013).
oral cancer (2 papers, 2014 to 2023). "In fact, HPV+ oral carcinomas overexpressed prostate stem cell antigen (PSCA) compared to HPV− oral carcinomas." (PMID 24719866, 2014). "This study permitted the proposal of 8 salivary biomarkers for oral cancer in patients previously infected with HPV (RPRD2, PSCA, MCM2, CDKN2A, BAK1, HSPA1A, TANK, MAP2K1)." (PMID 37599356, 2023).
pancreatic ductal adenocarcinoma (2 papers, 2020 to 2025). An infiltrating adenocarcinoma that arises from the epithelial cells of the pancreas. "Prostate stem cell antigen (PSCA) is highly and preferentially expressed on the surface of pancreatic ductal adenocarcinoma (PDAC) cells, raising the promise of tumor-selective cell-based immunotherapies." (PMID 40231460, 2025). "Indeed, a 4/7 ICR co-expressed in prostate stem cell antigen (PSCA)-directed CAR T-cells reversed immunosuppression and led to enhanced CAR T-cell-mediated cytotoxicity in a mouse model of pancreatic ductal adenocarcinoma." (PMID 33643299, 2020).
transitional cell carcinoma (2 papers, 2011 to 2015). A malignant neoplasm arising from the transitional epithelium, usually affecting the urinary bladder, ureter, or renal pelvis. "Therefore, the present study investigated the different expression levels of PSCA mRNA in transitional cell carcinoma (TCC) of the bladder and normal bladder tissue." (PMID 25624885, 2015).
type 2 diabetes (2 papers, 2012 to 2023). "Both type 2 diabetes (two at SND1–PAX4 locus and one at GAST locus) and GC (EFNA1, PTGER4 and PSCA loci) shared three significant variants after Bonferroni’s correction (P < 8.6 × 10−6) with PUD or its subtypes." (PMID 38036781, 2023).
urinary tract infection (2 papers, 2017 to 2024). "We found an association between urinary tract infections (UTIs) and variants in PSCA (rs2976388, P = 3.27 × 10−10, effect = 0.04)." (PMID 28928442, 2017).
autoimmune gastritis (1 paper, 2024). Inflammation of the body fundic mucosa of the stomach. "Epstein–Barr virus infection, autoimmune gastritis, germline mutations in the CDH1 gene, polymorphism in the prostate stem cell antigen, and familial adenomatous polyposis are known to be associated with HpUIGC." (PMID 38542051, 2024).
benign prostatic hyperplasia (1 paper, 2024). A non-cancerous nodular enlargement of the prostate gland. "Analysis of ISH and immunohistochemistry (IHC) showed that the expression of PSCA protein and mRNA in benign prostatic hyperplasia (BPH) and low-grade prostatic intraepithelial neoplasia (PIN) is weak or not expressed, but has a very high expression in high-grade form (HGPIN)." (PMID 38627732, 2024).
carcinoma in situ (1 paper, 2024). "PSCA mRNA is expressed in bladder tumors, including superficial transitional cell tumors (STCC), muscle-invasive TCCs (ITCCs), invasive transitional cell, carcinoma in situ (CIS), and even the dysplastic type, and its expression is much higher than normal tissue." (PMID 38627732, 2024).
Cholecystitis (1 paper, 2024). The presence of inflammatory changes in the gallbladder. "PSCA acts as down-regulation in this cancer, as in cholecystitis, mucinous adenocarcinoma, adenosquamous cell carcinoma, undifferentiated carcinoma, adenomyomatosis, and metaplasia its expression is down-regulated, but it is not clear for cholesterolosis or in polyp." (PMID 38627732, 2024).
chronic pancreatitis (1 paper, 2011). A chronic inflammatory process causing damage and fibrosis of the pancreatic parenchyma. "This study demonstrated that three genes, IGFBP3, SPINK1 and PSCA, can differentiate, in tissue samples, cancerous samples from benign samples (normal and chronic pancreatitis cases)." (PMID 21245863, 2011).
colorectal cancer (1 paper, 2015). A primary or metastatic malignant neoplasm that affects the colon or rectum. "A most recent study, however, even demonstrated no genotypic association between PSCA rs2294008 polymorphism and the risk of colorectal cancer." (PMID 26308216, 2015).
cyst (1 paper, 2018). A sac-like closed membranous structure that may be empty or contain fluid or amorphous material. "Studies of other preneoplastic lesion such as IPMN and other cystic precursor lesions of the pancreas identify the proteins TIMP1 in plasma, mucin-5AC, mucin-2, cyst-fluid carcinoembryonic antigen and prostate stem-cell antigen in cyst fluids as potential protein biomarkers." (PMID 29865155, 2018).
endometrial cancer (1 paper, 2024). Primary or metastatic malignant neoplasm involving the endometrium (mucous membrane that lines the endometrial cavity). "During the process of endometrial cancer (EAC), the presence of PSCA has also been identified and because in EAC, PSCA antigen is associated with age factor, it is considered as a marker for screening patients over 54 years." (PMID 38627732, 2024).
fungal infection (1 paper, 2017). "The increased abundances of chitinase (spot 18) and thaumatin-like protein (spot 23) in PsCA+CS cucumber than in the control following cold storage imply that these two PR proteins play an important role in defense against fungal infection." (PMID 29403505, 2017).
gallbladder adenocarcinoma (1 paper, 2013). A carcinoma that arises from glandular epithelial cells of the gall bladder. "The overexpression of PSCA and Oct-4 was significantly associated with differentiation, tumor mass, lymph node metastasis, invasion of gallbladder adenocarcinoma, and decreased overall survival." (PMID 23984394, 2013). "Moreover, PSCA and Oct-4 overexpression levels were important factors associated with the invasion, metastasis, and poor prognosis of gallbladder adenocarcinoma." (PMID 23984394, 2013). "In conclusion, our study revealed that the expression of PSCA and Oct-4 was increased in gallbladder adenocarcinoma." (PMID 23984394, 2013). "In this study, overexpression of PSCA and Oct-4 was detected in gallbladder adenocarcinoma (54.6% and55.6%)." (PMID 23984394, 2013). "Thus, overexpression of PSCA and/or Oct-4 can be used as a biological marker to predict the progression and prognosis of gallbladder adenocarcinoma." (PMID 23984394, 2013).
gastritis (1 paper, 2018). Inflammation of the stomach. "In addition, PSCA expression in severe gastritis patients was lower than in mild gastritis patients only among T carriers, but not among the CC genotype (CC: P = 0.36, CT: 0.048, TT: 0.032)." (PMID 29423095, 2018).
mastitis (1 paper, 2024). Inflammation of breast tissue during lactation or postpartum due to an obstructed duct or infection. "Among them, cnvr_137 contains genes such as LY6D, LYNX1, LYPD2, SLURP1,THEM6, PSCA, TSNARE1, and ARC associated to clinical mastitis in US Holstein dairy cows." (PMID 38771855, 2024).
metastasis (1 paper, 2024). The spread or migration of cancer cells from one part of the body (where they first appeared) to another. "PSCA overexpression in ESCC cancer is associated with some clinicopathological features such as poor differentiation, lymph node metastasis and advanced stage and is a tumor suppressor candidate in this cancer." (PMID 38627732, 2024).
oesophageal cancers (1 paper, 2020). "However, PSCA is expressed at low levels in gastric, gallbladder and oesophageal cancers." (PMID 32201541, 2020).
osteosarcoma (1 paper, 2023). A usually aggressive malignant bone-forming mesenchymal neoplasm, predominantly affecting adolescents and young adults. "Most gene targets commonly investigated in ACT of other solid tumors except osteosarcoma, such as CEACAM1, PSCA, MSLN, IL13RA2, and GPC3, showed low or nonspecific expression in osteosarcoma compared with adjacent normal tissues." (PMID 37457661, 2023).
prostate adenocarcinoma (1 paper, 2025). "Pulsation occurs with different peptides or combinations of peptides and prostate-specific membrane antigens (PSMA), androgen-sensitive human prostate adenocarcinoma cells (LNCaP), prostate acid phosphatase (PAP), or prostate stem cell antigen (PSCA)." (PMID 40430079, 2025). "Examples included prostate-specific membrane antigen (PSMA), androgen-sensitive human prostate adenocarcinoma cells (LNCaP), prostatic acid phosphatase (PAP), and prostate stem cell antigen (PSCA)." (PMID 40430079, 2025).
urinary system tumors (1 paper, 2024). "The availability of tumor-associated antigens in urinary system tumors, such as prostate stem cell antigen (PSCA), prostate specific membrane antigen (PSMA), and epidermal growth factor receptor (EGFR), makes CAR T cell therapy possible for urinary system tumors." (PMID 38789450, 2024).
tumor (65 papers, 2009 to 2025). "Prostate stem cell antigen (PSCA) is a glycosylphosphatidylinositol-linked cell-surface antigen that plays a critical role in promoting cell-cycle progression and boosting tumor cell proliferation." (PMID 40231459, 2025). "In the present study, PSCA mRNA was expressed at a significantly higher level in the tumor tissue of T allele carriers compared with CC homozygous patients (P=0.038)." (PMID 25624885, 2015). "Such a study has been completed for sporadic diffuse-type gastric cancer, which can be associated with H. pylori infection, revealing two candidate loci, one that encodes a likely tumor suppressor (prostate stem cell antigen [PSCA])." (PMID 19855816, 2009). "In addition, PSCA expression was significantly associated with specific molecular subtypes, tumour stage, grade, OS and immune cell subtypes in pan-cancer." (PMID 38917176, 2024). "In addition, tumor-associated antigens such as prostate stem cell antigen (PSCA), prostate specific membrane antigen (PSMA) and epidermal growth factor receptor (EGFR) are expressed in urologic neoplasms." (PMID 35860578, 2022). "Prostate stem cell antigen (PSCA) is highly expressed on the surface of tumor cells of most PDAC patients, with minimum expression in most normal tissues." (PMID 40231459, 2025). "Despite formidable barriers, several tumor-associated antigens—such as mesothelin (MSLN), prostate stem cell antigen (PSCA), carcinoembryonic antigen (CEA), HER2, MUC1, and CD133—are being explored as targets." (PMID 40700298, 2025). "LY6/uPAR superfamily members, such as LY6E, LY6H, LY6K, and PSCA, are overexpressed in various cancers and contribute to tumor growth, invasion, and metastasis." (PMID 39727968, 2024). "A multivariate analysis examined PSCA mRNA expression levels and their association with age, sex, disease recurrence, stage and grade of the tumor, and reported that PSCA expression was an independent prognostic factor for assessing tumor recurrence." (PMID 38627732, 2024). "CAR‐T cells with mucin‐1 (MUC1) and prostate stem cell antigen (PSCA) cannot eliminate tumor cells but the combined therapy showed a better anti‐tumor effect than single CAR‐T cell therapy." (PMID 38456710, 2024). "The genes PICK1 and PSCA are also both thought to play tumour suppressing roles in astrocytic and gastric epithelial cell cancers, respectively." (PMID 35774118, 2022). "In this work, we report on the targeted delivery of a therapeutic siRNA specific for BIRC5/Survivin in vitro and in vivo to tumor cells expressing the surface marker prostate stem cell antigen (PSCA)." (PMID 34066833, 2021). "The prostate stem cell antigen (PSCA) gene has tumor suppressor characteristics and inhibits cell production and/or death induction activities." (PMID 31983162, 2020). "Genes related to oxidative phosphorylation and those related with chemoresistance and poor prognosis such as HNRNPA0, HDAC1, LDHB, AREG, and PSCA were upregulated in subgroups of brain metastasis-derived tumor cells in chemotherapy treated patients." (PMID 33170151, 2020). "So far, a series of TMs against a variety of tumor targets including against the prostate stem cell antigen (PSCA) were constructed and functionally characterised." (PMID 31332252, 2019). "A similar approach has been used to increase the intensity of other tumour-associated antigens, i.e., mucin-1 (MUC-1) and prostate stem cell antigen (PSCA)." (PMID 27580852, 2016). "In conclusion, the present study demonstrated that PSCA mRNA was more highly expressed in T allele carriers compared with CC homozygous patients, and PSCA mRNA expression was associated with TCC and tumor histological grade." (PMID 25624885, 2015). "Interestingly, PSCA is also overexpressed in a variety of other tumor entities including gallbladder-, urinary bladder-, breast-, and pancreatic cancer, as well as renal cell carcinomas and gliomas." (PMID 37298374, 2023).